KLF5 (KLF transcription factor 5)
Diseases named in the same sentence as KLF5 in open-access papers (continued):
Sharing a sentence is not in itself a finding about the gene and the disease.
colitis (7 papers, 2012 to 2026). Inflammation of the colon. "The first colitis mouse model is the genetic Villin-CreERT2;Klf5fl/fl (Klf5ΔIND) model, wherein an inducible intestinal epithelium-specific knockout of Klf5 causes colitis." (PMID 37658187, 2023). "Inducible intestinal-epithelium specific deletion of KLF5 impairs this replenishment to cause impaired epithelial barrier function and Th17-dependent colitis with pathological features and microbiotic changes reflective of human IBD23." (PMID 37658187, 2023). "We utilized the dextran sodium sulfate (DSS) colitis model and the Villin-CreERT2;Klf5fl/fl (Klf5ΔIND) model, wherein inducible intestinal epithelium-specific knockout of Klf5 disrupts barrier function and causes colitis." (PMID 37658187, 2023). "In contrast, mitigation of IL-17A with anti–IL-17A neutralizing antibody attenuated colitis in Klf5-deficient mice." (PMID 35393949, 2022). "Neutralization of IL-17A by antibody attenuates colitis in Klf5-deficient mice." (PMID 35393949, 2022). "The correlation between reduced KLF5 levels and colitis suggested that KLF5 may play a pathogenic role, prompting us to examine the mouse intestine after KLF5 ablation." (PMID 35393949, 2022). "Importantly, heterozygous Klf5-KO mice are more susceptible to dextran sulfate sodium–induced (DSS-induced) colitis than WT mice." (PMID 35393949, 2022). "Interestingly, STAT3 activation in enterocytes may also increase the development of colitis-associated cancer; thus the long-term effects of KLF5-mediated STAT3 induction in colitis merit further study." (PMID 22675454, 2012). "Collectively, these results indicate that KLF5 plays a pivotal role in the repair of intestinal mucosal damage and the maintenance of intestinal homeostasis in colitis." (PMID 41513630, 2026). "In colonic tissues, constitutive KLF5 overexpression protects against murine colitis under the inflammatory stimulus." (PMID 36982414, 2023). "Mice with intestinal epithelium-specific deletion of Klf5 also developed a Th-17-mediated immune response and subsequent colitis, suggesting a protective role of KLF5 against intestinal inflammation." (PMID 37173904, 2023). "Consistently, WT mice have an increased level of KLF5 in the crypt epithelium upon DSS treatment, suggesting that KLF5 is important in guarding against DSS-induced colitis." (PMID 35393949, 2022). "We first evaluated the role of KLF5 in the pathogenesis of human colitis by measuring its levels in patient samples." (PMID 35393949, 2022). "Inducible intestinal epithelium-specific knockout of Klf5 upon five days of intraperitoneal (IP) tamoxifen (TAM) injections disrupts epithelial barrier function and causes colitis (5T-Klf5ΔIND)." (PMID 36037173, 2022). "Mice with intestinal epithelium–specific deletion of Klf5 develop colitis and have decreased survival." (PMID 35393949, 2022). "During colitis with intact KLF5, IL-22 helps signal regeneration in the intestinal epithelium through p-STAT3 signaling." (PMID 35393949, 2022). "KLF5 promotes rapid cell proliferation, migration, and remodeling, and mice with hemizygous deletion of Klf5 have greater sensitivity to dextran sodium sulfate (DSS) colitis than wild-type mice." (PMID 22675454, 2012). "We then treated Villin-Klf5 transgenic mice with DSS to induce colitis and examine the effect of KLF5 on intestinal injury and restitution in vivo." (PMID 22675454, 2012). "The results presented here demonstrate that epithelial-specific expression of KLF5 protects against the development of colitis in vivo." (PMID 22675454, 2012). "In sum, we have used a novel transgenic mouse model to demonstrate an essential role for KLF5 in intestinal epithelial homeostasis and in mucosal healing following induction of experimental colitis." (PMID 22675454, 2012). "Recently, mice with hemizygous deletion of Klf5 were found to have greater sensitivity to DSS colitis than wild-type mice." (PMID 22675454, 2012). "KLF5 is reduced in the colon of patients with active colitis." (PMID 35393949, 2022).
colitis (continued). "We have also elucidated the mechanism by which KLF5 guards against the development of colitis." (PMID 35393949, 2022). "Thus far, our data suggest that Klf5 deletion from the intestinal epithelium leads to an inflammatory response and potentiates the development of colitis." (PMID 35393949, 2022). "First, we observed a dose-dependent response between KLF5 expression and the severity of colitis." (PMID 35393949, 2022). "Antibiotic treatment abrogates Klf5 deletion–induced colitis." (PMID 35393949, 2022). "However, when Villin-Klf5 mice were treated with dextran sodium sulfate (DSS) to induce colitis, they developed less colonic injury and significantly reduced disease activity scores than littermate controls." (PMID 22675454, 2012). "Thus KLF5 and STAT3 signaling provide important areas for further study in colitis and represent potential diagnostic and therapeutic targets for IBD and other diseases characterized by injury and disruption of intestinal epithelia." (PMID 22675454, 2012). "Given these functions, we hypothesized that constitutive Klf5 expression would protect against the development of colitis in vivo." (PMID 22675454, 2012). "Combined with the observation that KLF5 was lower in active UC, results of these experiments implicate a role for KLF5 in modulating p-STAT3 signaling in human colitis as well." (PMID 35393949, 2022). "Villin-Klf5 and control mice were challenged with 3.5% DSS for 7 days to induce experimental colitis." (PMID 22675454, 2012). "Collectively, these results showed that colitis resulting from the absence of epithelial KLF5 was rescued by antibiotic treatment, suggesting that intestinal microbiota played a vital role in mediating the colitis phenotype in these mice." (PMID 35393949, 2022). "However, to date, the effect of increased KLF5 in intestinal epithelia in vivo has not been examined, and a protective effect of constitutive intestinal KLF5 expression on colitis has not yet been demonstrated." (PMID 22675454, 2012).
COVID-19 (7 papers, 2022 to 2025). A disease caused by infection with severe acute respiratory syndrome coronavirus 2. "Specifically, ALDH1L2 (AUC: 1) showed the best diagnostic efficiency for differentiation in the COVID-19 dataset, whereas KLF5 (AUC: 0.803) demonstrated the best discriminatory ability in the sarcopenia dataset." (PMID 38978778, 2024). "The ROC curves for ALDH1L2 and KLF5 genes demonstrated their potential as diagnostic markers for both sarcopenia and COVID-19." (PMID 38978778, 2024). "The variants in KLF5 genomic region and reduced KLF5 expression are associated with severe COVID-19 patients." (PMID 38168026, 2024). "Furthermore, we discover another anti-viral regulator KLF5, a transcriptional factor involved in sphingolipid metabolism, which is up-regulated, and harbors genetic variations linked to COVID-19 patients with severe symptoms." (PMID 38168026, 2024). "Furthermore, we discovered an anti-viral regulator KLF5, a transcriptional factor involved in sphingolipid metabolism, which was up-regulated and harbored genetic variations linked to the COVID-19 patients with severe symptoms." (PMID 36032971, 2022). "Jiakai Hou and Janneh A. H respectively pointed out that KLF5 was significantly correlated with the occurrence, development and severity of COVID-19 through multi-omics and clinical observation analysis." (PMID 38600309, 2024). "Molecular characterization of DAZAP2/VTA1/KLF5-knockout cells highlights the involvement of genes related to the coagulation system in determining the severity of COVID-19." (PMID 38168026, 2024). "SRPK1, CSGALNACT2, B4GALT5, MEGF9, and KLF5 have increased mRNA expression in patients with severe COVID-19 compared with mild and non-COVID-19 patients." (PMID 38262689, 2024). "Four of these genes (ACE, KLF5, IDO1, and CDC25A) have been reported to be associated with the pathological mechanisms of COVID-19 and sarcopenia." (PMID 38978778, 2024). "Interestingly, KLF5 (anti-viral factor) also displays a concordant change when comparing gene expression between severe and mild COVID-19 patients." (PMID 38168026, 2024). "Last, we observed strong correlations between COVID-19 severity and KLF5 expression." (PMID 38168026, 2024). "KLF5, one of the top 10 anti-viral factors, was also selected because of its clinical relevance as indicated by both GWAS analysis and transcriptome analysis of COVID-19 patients." (PMID 38168026, 2024). "We also found that KLF5, a transcription factor of the Krüppel-like factor subfamily of zinc finger proteins that showed anti-viral activity in our CRISPR screen, was associated with COVID-19 hospitalization and severe symptoms." (PMID 38168026, 2024). "In addition, we used multiple machine learning methods to screen for five risk genes (KLF5, NSUN7, APH1B, GRB10 and CD4), which are used to predict COVID-19 severity." (PMID 38600309, 2024). "In goblet cells, STAT2 and KLF5 were highly activated and upregulated in many genes with mild/moderate COVID-19, such as ISGs (PARP14 and IFI44L), whereas ELF3, SBP1, NR2F6, and SPDEF were preferentially activated in severe COVID-19 to regulate the expression of their targets." (PMID 37936693, 2023). "For example, compared to activated STAT2 and KLF5 in mild/moderate goblet cells, SPDEF, ELF3, XBP1, and NR2F6 were found activated in patients with severe COVID-19." (PMID 37936693, 2023). "For example, RFX2 and RFX3 showed high activity in ciliated cells regardless of disease severity, while XBP1, NR2F6, SPDEF, and ELF3 were preferentially activated in goblet cells in patients with severe COVID-19, and KLF5 and STAT2 were coactivated in patients with mild/moderate COVID-19." (PMID 37936693, 2023).
diabetic cardiomyopathy (7 papers, 2018 to 2025). Diabetic cardiomyopathy is a disorder of the heart muscle in people with diabetes. "To characterize the mechanism through which chemotherapeutic drugs down-regulate KLF5 expression in BLBC, we searched the literature and found that FOXO1 induces KLF5 transcription and causes oxidative stress in diabetic cardiomyopathy." (PMID 37588224, 2024). "Also, given the involvement of KLF5 in diabetic cardiomyopathy, it is also relevant that, miR-145, and miR-375 target KLF5, thereby repressing its levels." (PMID 37226245, 2023). "In addition, FOXO1 promoted KLF5 transcription in diabetic cardiomyopathy." (PMID 37588224, 2024). "In addition, KLF5 contributes to oxidative stress and diabetic cardiomyopathy." (PMID 35528516, 2022).
esophageal adenocarcinoma (7 papers, 2019 to 2025). A malignant tumor with glandular differentiation arising predominantly from Barrett mucosa in the lower third of the esophagus. "Taken together, our findings identify KLF5 as a potential oncogene in esophageal adenocarcinoma and suggest a novel connection between KLF5 and the SHH pathway." (PMID 31401336, 2019). "For instance, in esophageal adenocarcinoma, SEs that are specific to this type of cancer regulate the overexpression of pro-carcinogenic transcription factors like ELF3, KLF5, GATA6, and EHF." (PMID 38443991, 2024).
leukemia (7 papers, 2013 to 2022). A malignant (clonal) hematologic disorder, involving hematopoietic stem cells and characterized by the presence of primitive or atypical myeloid or lymphoid cells in the bone marrow and the blood. "In order to determine whether Klf5 deficiency impairs B-cell leukemogenesis once leukemia have been initiated, we generated Mx1-Cre;Klf5flox/flox mice where the deficiency of Klf5 can be induced after transplantation in recipient mice where leukemogenesis has already been initiated." (PMID 30038712, 2018). "Our data herein demonstrated the high level of lncRNA HOTAIRM1 in NPM1-mutated leukemia cells and indicated that HOTAIRM1 was upregulated at least partially by mutant NPM1 via KLF5-dependent transcriptional regulation." (PMID 34615546, 2021). "For example, KLF5 binds to the promoter of the survivin gene to induce the expression of survivin in leukemia, which leads to increased cell survival." (PMID 23755247, 2013). "In addition, three integration sites of the RV vector were found within cancer-related genes (Klf5, NUMB, and FHIT), all of which are associated with leukemogenesis or leukemia progression." (PMID 23990961, 2013). "However, the KLF5 promoter has been found to be hyper-methylated in BCR-ABL1 expressing B-ALL, suggesting that KLF5 transcriptional regulation may be relevant and as such it may act as a tumor suppressor in this specific type of leukemia." (PMID 30038712, 2018).
myocardial infarction (7 papers, 2019 to 2025). Gross necrosis of the myocardium, as a result of interruption of the blood supply to the area, as in coronary thrombosis. "Cardiomyocyte KLF5 expression is increased in mice with myocardial infarction or patients with ischemic heart failure, and genetic or pharmacological inhibition of KLF5 can increase ejection fraction." (PMID 36135378, 2022). "Collectively, our data identify a novel function of lncR-TUG1/miR-9/KLF5 axis in regulating cardiomyocyte apoptosis that affects myocardial infarction progression." (PMID 31787746, 2019). "Recent studies have elucidated the significant involvement of the HDC/histamine signal in the regulation of the transformation of bone marrow-derived macrophages into cardiac myofibroblasts via a HR/KLF5 dependent signaling pathway in acute myocardial infarction mice." (PMID 40303294, 2025). "According to research, KLF5 regulates ceramide accumulation and lipid metabolism after Myocardial Infarction (MI)." (PMID 38516000, 2024). "Consequently, a therapeutic strategy involving the modulation of KLF5 or miR-152-3p in conjunction with stem cell therapy emerges as a promising and innovative approach for myocardial infarction (MI) treatment." (PMID 40822849, 2025).
squamous cell carcinoma (7 papers, 2012 to 2025). A carcinoma arising from squamous epithelial cells. "In squamous cell carcinoma, KLF5 positively regulates Sox4 expression, and KLF5/Sox4 regulatory signaling facilitates tumorigenesis." (PMID 41465103, 2025). "In addition, Studies have demonstrated that SREBF1 forms a reciprocal regulatory loop with TP63/KLF5 to promote survival and migration in squamous cell carcinoma." (PMID 40668814, 2025). "Especially, KLF5 activates cell identity genes and cancer genes in squamous cell carcinomas." (PMID 32460441, 2020).
acute lymphoblastic leukemia (6 papers, 2008 to 2023). Leukemia with an acute onset, characterized by the presence of lymphoblasts in the bone marrow and the peripheral blood. "It has also been reported that KLF5 up-regulated anti-apoptotic BIRC5 in human pulmonary vascular smooth muscle cells and acute lymphocytic leukemia cell lines." (PMID 26474386, 2015).
acute myeloid leukemia (6 papers, 2018 to 2023). Acute myeloid leukemia (AML) is a group of neoplasms arising from precursor cells committed to the myeloid cell-line differentiation. "Hypermethylation of KLF5 intron 1 was also associated with decreased KLF5 expression in acute myeloid leukaemia and was related to poor overall survivial." (PMID 33523554, 2021). "The rates of KLF5 variation ranged from 3.6% (acute myeloid leukemia, LAML) to 76.8% (uterine carcinosarcoma, UCS)." (PMID 33923166, 2021). "However, in prostate, esophageal squamous cell cancers and acute myeloid leukemia (AML), KLF5 inhibits cell proliferation and promotes cell differentiation, acting as a tumor suppressor." (PMID 30038712, 2018).
intestinal tumors (6 papers, 2010 to 2021). "We conclude that Klf5 is a crucial mediator of initiation and progression of intestinal tumors resulted from ApcMin and KRASV12 mutations." (PMID 20298593, 2010). "Here we investigated the in vivo effect of Klf5 heterozygosity on the propensity of ApcMin/KRASV12 double transgenic mice to develop intestinal tumors." (PMID 20298593, 2010). "The drastic reduction in tumor number and size due to Klf5 heterozygosity in ApcMin/KRASV12 mice indicate a critical function of KLF5 in modulating intestinal tumor initiation and progression." (PMID 20298593, 2010). "In contrast, both ApcMin/KRASV12 and ApcMin/KRASV12/Klf5+/- mice contained a higher percentage of intestinal tumors in the proximal small intestine, duodenum (44% and 64%, respectively) when compared to the ApcMin mice (7%)." (PMID 20298593, 2010). "We also stained intestinal tumors derived from ApcMin, ApcMin/KRASV12 and ApcMin/KRASV12/Klf5+/- mice for Klf5 and β-catenin." (PMID 20298593, 2010).